BECN1 (beclin 1)
Diseases named in the same sentence as BECN1 in open-access papers (continued):
Sharing a sentence is not in itself a finding about the gene and the disease.
tumor (continued). "It suggested that LC3 and Beclin-1 are required for cell proliferation, survival, migration and invasion and may contribute to the tumour growth and progression of highly aggressive and metastatic TNBC tumours." (PMID 32961774, 2020). "However, further studies on the suitability of Beclin 1 as an anti-tumour target would be required to develop a novel therapeutic target in anti-tumour therapy involving necroptosis." (PMID 32457484, 2020). "However, the loss of either BECN1, LC3B, or both was associated with a higher percentage of CNA alterations within the tumor." (PMID 31923184, 2020). "The mechanisms by which Beclin-1 negatively modulates tumor growth are not fully understood." (PMID 33330070, 2020). "Furthermore, Beclin-1’s aberrant expression correlates with poor prognosis for different tumor types, such as HCC." (PMID 32121322, 2020). "Beclin‐1 is involved in the nucleation of the autophagic vesicles and could be regulated by autophagy during tumor progression as the tumor suppressor gene." (PMID 32750222, 2020). "Beclin-1 is a protein that has been correlated to tumour suppression." (PMID 33704184, 2020). "The importance of EGFR-phosphorylated Beclin 1 in tumorigenesis is highlighted by xenograft experiments, where NSCLC (non-small cell lung cancer) cells expressing a constitutively phosphorylated Beclin 1 mutant inhibit autophagy and enhance tumor growth and proliferation." (PMID 33287140, 2020). "There are different examples of cancer types in which autophagy has a tumor suppressive role as in PTEN and Beclin 1 knockouts and others in which autophagy sustains tumor growth in these cases the inhibition of autophagy represents a promising therapeutic approach." (PMID 32244996, 2020). "Beclin 1 suppressed the tumor growth by decreasing proliferation and increasing apoptosis." (PMID 33425768, 2020). "Consequently, the experimental evidence presented suggests that beclin-1 functions as a haplo-insufficient tumor suppressor gene." (PMID 33297472, 2020). "The haploinsufficient tumor suppressor and critical autophagy effector protein Beclin 1 (the mammalian ortholog of yeast Atg6) is also a key member of the PI3K complex, and can regulate autophagy through its ability to interact with members of the anti-apoptotic BCL-2 family." (PMID 32195258, 2020). "BECN1, also known as beclin 1, has been highlighted for its tumor suppressor roles ever since two independent labs generated heterozygous whole-body knockout mouse models; each study observed earlier cancer formation in Becn1+/- mice compared to Becn1+/+ mice." (PMID 31923184, 2020). "Spontaneous formation of lung carcinoma and hepatocellular carcinoma is observed in mice with a heterologous deletion of BECN1, suggesting that some components of the autophagic machinery may behave as tumor suppressors." (PMID 33363032, 2020). "Beclin-1 was taken as an independently predicted marker of HCC tumor progression." (PMID 33260729, 2020). "Furthermore, autophagy pathway activation by Tat-Beclin-1, a direct autophagic-mechanism inducer, selectively promotes ferroptotic cell death in tumor cells." (PMID 33194736, 2020). "The autophagy-independent function of Beclin 1 in necroptosis provides an insight into the molecular mechanism of cell death and has therapeutic implications in necroptosis-related diseases and anti-tumour therapies." (PMID 32457484, 2020). "This tumour-suppressive role of autophagy is supported by early studies that showed increased development of spontaneous, potentially benign, lung and liver tumours and lymphomas in mice deleted of autophagy genes Beclin 1, Atg7 and Atg5." (PMID 32873152, 2020). "However, if autophagy is blocked by deletion of BECN1, granzyme B levels are restored and favors tumor regression in vivo due to tumor cell death by NK-mediated lysis." (PMID 33324568, 2020).
tumor (continued). "Basing on this finding, the results concerning Beclin-1 expression in our study population lead us to hypothesize that a similar scenario could have important effects on tumor angiogenesis in UM." (PMID 33330070, 2020). "Beclin-1 alteration was reported in several forms of tumour cells." (PMID 33704184, 2020). "Similarly, we detected the expression of BECN1 to be upregulation in tumor tissues and HCC cells at mRNA level (P <0.05) and protein level (P <0.05)." (PMID 30696802, 2019). "On the other hand, BECN1 was also reported to promote tumor migration." (PMID 31272261, 2019). "Consistent with this notion, we found that inhibiting autophagy by targeting the key autophagy gene Becn1, which led to a substantial decrease in extracellular TRAPs, could inhibit tumor growth in mice." (PMID 31300052, 2019). "Besides, the frequency of IFN-γ-producing CD4+ T cells and CD8+ T cells in Becn1 knock-down tumor tissue was markedly increased." (PMID 31300052, 2019). "Similarly, expression of the exogenous autophagy gene Beclin-1 induces autophagy in tumor-resistant lung cancer cells and inhibits tumor cell growth and angiogenesis." (PMID 31598167, 2019). "In BECN1 ± mouse, cell death was increased in tumor hypoxic region." (PMID 31272261, 2019). "Indeed, inhibition of the autophagy gene BECN1 in solid tumours induced a massive NK cells infiltration leading to tumour growth inhibition." (PMID 30704144, 2019). "Based on these observations, it is speculated that Beclin 1 may work through induction of autophagy to negatively regulate tumor progression." (PMID 31065032, 2019). "Having shown a critical role of TRAPs in the inhibition of anti-tumor immunity, we explored whether inhibition of TRAPs formation by targeting Becn1, a gene essential for autophagosome formation, could abolish the generation of tumor-promoting TTRAP." (PMID 31300052, 2019). "Interestingly, Beclin-1 is an essential protein for autophagy which play multiple roles in tumor progression and suppression." (PMID 30849962, 2019). "Indeed, Beclin 1 overexpression or Tat-Beclin 1 treatment increases ferroptosis cell death and decreases tumor growth in vivo." (PMID 31877888, 2019). "However, autophagy can also play a pro-tumor role in carcinogenesis by regulating a number of pathways, including Beclin-1, Bcl-2, Class III and I PI3K, mTORC1/C2, and p5314,15." (PMID 29549251, 2018). "The oncogenic EGFR was recently shown to aberrantly bind to Beclin-1, which might contribute to tumor progression and chemoresistance." (PMID 30237564, 2018). "We observed increased content of lipidated LC3, increased ratio of LC3II and LC3I (LC3II/LC3I), Lc3b mRNA and Beclin-1 in the skeletal muscle of C26 tumor-bearing mice, which indicates increased autophagosome content and the induction of autophagy, respectively." (PMID 30713500, 2018). "Additionally, autophagy markers LC3II/I (p < 0.05), Beclin-1 (p < 0.01), and P62 (p < 0.05) increased in the skeletal muscle of tumor-bearing mice." (PMID 30713500, 2018). "In addition, H&E staining showed that administration of TAN‐induced cell structure deterioration in tumor tissues, and even with Beclin‐1 knockdown, the effect was observed with H&E staining." (PMID 29316373, 2018). "The initial indication that autophagy could have an important role in tumor suppression came from several studies exploring the essential autophagy gene BECN1, which encodes the Beclin-1 protein, in different cellular models." (PMID 30540126, 2018). "Finally, as everolimus has been reported to induce autophagy in other tumour cell lines and increases expression of the marker of autophagy, beclin‐1, we examined its effect on beclin expression in BTC lines." (PMID 28544747, 2017).
tumor (continued). "It has been hypothesized that BECN1 acts as tumor suppressor gene, because of its frequent deletion in a variety of tumors such as breast, ovarian and prostate." (PMID 28035578, 2017). "In addition, several autophagic proteins can directly suppress tumour formation (e.g. Beclin-1, UVRAG and Bif-1) and autophagy has been shown to degrade tumour promoting proteins as well (e.g. p62/SQSTM1)." (PMID 29225688, 2017). "In addition to the role of Beclin 1 in autophagy, it also functions as a tumor suppressor in mammalian cells." (PMID 29079782, 2017). "Here, miR-409-3p-targeted BECN1/Beclin 1 and sensitized tumor cells to chemotherapy." (PMID 28459042, 2017). "Further, LY3023414's anti-tumor activity was augmented against Beclin-1-silenced tumors." (PMID 29228741, 2017). "In summary, our study provides further insight into the impact of Beclin 1 phosphorylation on the autophagy potential of tumor cells and presents evidence for the role of autophagy induced by CaMKII phosphorylation of Beclin 1 in solid tumor cell differentiation." (PMID 29079782, 2017). "Besides autophagy, other membrane-trafficking functions are also depend on Beclin 1, so we can't affirmatively claim that autophagy suppression rather than other destruction of membrane-trafficking events contributes to tumor growth." (PMID 28099922, 2017). "Moreover, at the end of the 21-day period, the expression levels of the autophagy-related molecules LC3, Atg5-12 complex, and Beclin-1 were significantly higher in tumor tissues from mice subjected to IMQ treatment combined with IR exposure." (PMID 28212561, 2017). "TW-37’s anti-tumor activity was further potentiated against Beclin-1-silenced HCT-116 tumors." (PMID 29065135, 2017). "Although, autophagy is often considered as a pro-survival mechanism protecting the cell against dwindling nutrient resources, studies in the beclin 1 autophagy gene knockout mice suggest that autophagy may also have a tumor suppressor function." (PMID 28785242, 2017). "We also checked if autophagy might be induced when tumor cells were cultured with continuous or pulsed T treatments by analyzing the levels of Beclin-1 and p62." (PMID 29371946, 2017). "Beclin 1 expression is also closely related with the effect of tumor treatments." (PMID 28881721, 2017). "Indeed, inhibition of autophagy using siRNAs directed against ATG5 or BECN1 restored tumor cells sensibility to CTL-mediated lysis." (PMID 26910842, 2016). "Furthermore, in NSCLC tumor xenografts, the expression of a tyrosine phosphomimetic Beclin-1 mutant led to reduced autophagy, enhanced tumor growth and resistance to TKI therapy." (PMID 30370422, 2016). "In this study, we provide evidence that downregulation of ASPP2 may contribute to tumor progression and chemoresistance via promoting BECN1-dependent autophagy in HCC." (PMID 27929538, 2016). "Significantly, Beclin 1, an autophagy gene has been shown as tumor suppressor." (PMID 27445685, 2016). "Beclin 1 is therefore generally considered as a haploinsufficient tumor suppressor gene." (PMID 27683118, 2016). "For example, a dose- and time-dependent induction of autophagy occurs in tumor cells following cisplatin treatment, as demonstrated by up-regulation of autophagy-inducing protein Beclin-1 and the subsequent development of acridine orange-stained acidic autophagic vesicles." (PMID 27043621, 2016). "A significant correlation between the BECN1 expression and tumor volume was observed (P=0.002)." (PMID 27929538, 2016). "Notably, three out of four tumor (75%) clinical samples bearing BRAFV600E have shown high mRNA expression of BECN1 and LC3 with respect to the matched normal tissue." (PMID 26802026, 2016). "Importantly, in the ASPP2 low group, a significant correlation between the presence of BECN1 and advanced tumor volume was observed (P=0.008)." (PMID 27929538, 2016).
tumor (continued). "Thus, when tumor cells are starved from nutrients, oxygen, and blood flow, Beclin-1-mediated autophagy stops cancer cells from dying due to inhibition of apoptosis." (PMID 27043621, 2016). "A recent study revealed that Beclin-1 expression levels differed between types of tumor cell." (PMID 25789037, 2015). "Therefore, we identify the molecular mechanism by which acetylation regulates Beclin 1 function in autophagosome maturation and tumour growth." (PMID 26008601, 2015). "To determine whether the acetylation of Beclin 1 also rendered growth advantage to tumour cells in vivo, we performed tumour xenograft studies." (PMID 26008601, 2015). "Therefore, our study identifies an acetylation-dependent regulatory mechanism governing Beclin 1 function in autophagosome maturation and tumour growth." (PMID 26008601, 2015). "As the expression of Beclin 1 2KR mutant showed a more remarkable inhibition on tumour growth than the WT group, we speculated that the tumour suppressor function of Beclin 1 might be achieved through its deacetylation." (PMID 26008601, 2015). "On the other hand, deletion of Beclin-1 results in tumor cell death in hypoxic regions." (PMID 25704884, 2015). "While we cannot exclude the possibility that autophagy may initially be disrupted by single allele loss of BECN1 to promote ovarian tumorigenesis, we have clearly shown that Beclin-1 is present in advanced-stage tumors and tumor cells." (PMID 26239434, 2015). "Beclin 1 was initially to be found to have tumor suppressor function." (PMID 26506105, 2015). "However, the validity of this comparison is difficult to assess, since epithelial cells (which have very high levels of BECN1 expression) comprise the majority of cells in tumor samples but only a small proportion of cells in normal breast tissue." (PMID 25825707, 2015). "In addition to participating in the regulation of autophagy, Beclin-1 has been demonstrated to play important roles in tumor suppression, cell death and development." (PMID 25944062, 2015). "Beclin-1 expression may be a useful biomarker of development of residual disease and tumor overexpression has revealed an additional therapeutic option with the use of proteasome inhibitor therapy." (PMID 25487826, 2015). "Our present findings suggest that CK1γ2 may implicate in tumour progression via promoting Beclin 1 acetylation and suppression of autophagosome maturation." (PMID 26008601, 2015). "Compared with patients in the group with high expression of BECN1, patients in the low expression group were more likely to accompany with deeper tumor invasion (P = 0.074) and lymph node metastasis (P = 0.061), although these differences were not statistically significant." (PMID 26497999, 2015). "Here we describe a novel role for members of the stress-activated protein kinase (p38 MAPK) signaling pathway, MAPKAPK2 (MK2) and MAPKAPK3 (MK3), in mediating Beclin 1 S90 phosphorylation, which we show is essential for its autophagy and tumor suppressor function." (PMID 25693418, 2015). "In addition molecular analyses of tumors in Beclin 1 heterozygous mice confirmed that Beclin 1 is a haploinsufficient tumor suppressor." (PMID 25821782, 2015). "Thus, deacetylation of Beclin 1 by the mutation of K430 and K437 sites in MCF7 xenografts results in increased autophagy flux, decreased cellular proliferation and tumour growth." (PMID 26008601, 2015).
tumor (continued). "& L.M. Perry (Myrtaceae), presence of autophagy inhibitor 3-MA or siRNA against Beclin-1 or Atg5 could restore proliferation of tumor cells." (PMID 25821829, 2015). "Conversely, low level of BECLIN 1 expression correlated with histologic grade III tumours." (PMID 25136588, 2014). "Indeed, in Beclin 1 + ∕− transgenic mice, that display reduced macroautophagy levels, a significant increase of spontaneous tumor incidence is observed." (PMID 25324830, 2014). "Conversely, autophagy can also inhibit tumor growth via beclin 1, UVRAG, Bif and Atg." (PMID 24676394, 2014). "The aberrant expression of Beclin-1 in many kinds of tumor tissues correlates with poor prognosis." (PMID 25317422, 2014). "A high proportion of BECLIN 1-positive cells was reported in 41 out of 61 tumours." (PMID 25136588, 2014). "Beclin 1 functions as a scaffold for the formation of autophagosomes and may be a haploin-sufficient tumor suppressor." (PMID 25196438, 2014). "We propose that the UVRAG-containing PI3K (III) complex II may act as a tumor suppressor, and such a role of Beclin 1 may be masked by its essential function during autophagy, as established cancer cells often depend on autophagy." (PMID 25006588, 2014). "For example, the core autophagy protein BECN1 (Beclin 1) is a tumor suppressor." (PMID 25490155, 2014). "In addition, studies in mice have demonstrated that the animals are more sensitive to spontaneous tumor development when beclin-1 is monoallelically disrupted." (PMID 25328887, 2014). "With regard to the distinct prognostic impact of Beclin 1 protein in various types of tumors, we speculate that it might be dependent on intrinsic properties of the tumor type, as well as the nature of the therapeutic regimen in various types of human cancers." (PMID 24260370, 2013). "In addition, tumour suppressors such as Beclin 1, PTEN and DAP kinase are known to positively regulate autophagy." (PMID 23933736, 2013). "Overall, the data suggest that Beclin-1 is a tumour suppressor gene." (PMID 23765161, 2013). "They concluded that beclin-1 was a pro-tumor factor in cancer development." (PMID 24122254, 2013). "Indeed, accumulated studies had confirmed the relationship between Beclin 1 and tumor metastasis in a series of tumors." (PMID 24303007, 2013). "Furthermore, correlation analysis demonstrated that Beclin 1 expression was negatively correlated with tumor recurrence rate in both sets (p < 0.001 in the training set and p = 0.001 in the testing set)." (PMID 24260370, 2013). "Consistent with most of the previous studies, our results showed that Beclin 1 protein was down-regulated in NSCLC and low expression of Beclin 1 was significantly associated with poor prognosis, indicating the potential tumor suppressing role of Beclin 1 in this tumor." (PMID 24260370, 2013). "In addition, Beclin 1 expression also negatively correlated with the initial tumor stage (p < 0.001)." (PMID 24260370, 2013). "Univariate survival analysis using the Kaplan-Meir method revealed that age, tumor size, tubular formation, nuclear pleomorphism, mitotic count, histologic grade, lymphovascular invasion, necrosis, and Beclin-1 cytoplasmic expression were significant prognostic factors for overall survival." (PMID 23578251, 2013). "The results suggest that Beclin-1 plays an important role in tumor progression of malignant CMTs." (PMID 23578251, 2013). "Our results showed that Beclin 1, as detected by immunohistochemistry, was significantly lower in NSCLC tissues compared with the adjacent normal tissues, and negatively associated with tumor recurrence rate." (PMID 24260370, 2013). "Our findings in the present study provided evidence that Beclin 1 may thus emerge as an independent prognostic biomarker in this tumor entity in the future." (PMID 24260370, 2013).